VCAM1 (vascular cell adhesion molecule 1)
Diseases named in the same sentence as VCAM1 in open-access papers (continued):
Sharing a sentence is not in itself a finding about the gene and the disease.
atherosclerosis (continued). "It has been reported that endothelial Cx43 expression regulates monocyte‐endothelial adhesion, which is a crucial initiator of atherosclerosis development, as increased Cx43 expression enhanced the expression level of cell adhesion proteins, including VCAM-1." (PMID 33388835, 2021). "VCAM1 is a key player in facilitating atherosclerosis by aiding in the local attachment and transmigration of inflammatory cells through the vascular endothelium." (PMID 33971895, 2021). "Thrombin-cleaved PAR1 was associated with increased plasma biomarkers such as VCAM1, ICAM-1, and E-selectin in 190 high-risk patients (CRP of mg/L 7.4 ± 6.7 mean ± SD) with chronic CVD due to atherosclerosis." (PMID 34944024, 2021). "VCAM-1 is major contributor in the initiation of atherosclerosis and is commonly detected in ~82% of vascular plaques." (PMID 33925294, 2021). "VCAM-1 is rapidly overexpressed in the first stages of atherosclerosis, thus representing a promising target for early atheroma detection." (PMID 34371717, 2021). "ICAM-1 binding to integrins produces proinflammatory effects, and VCAM-1 has been reported to be involved in developing atherosclerosis." (PMID 33603819, 2021). "It has been suggested that VCAM-1 is involved in the development of several process such as rheumatoid arthritis, atherosclerosis and DKD." (PMID 33976959, 2021). "A previous study has shown that in patients with atherosclerosis proteinuria correlated with circulating levels of soluble vascular cell adhesion molecule-1 (VCAM-1)." (PMID 34071993, 2021). "To determine if expression of VCAM-1 precedes atherosclerosis, we measured expression of this adhesion molecule in aortic tissue of Wistar rats." (PMID 38046985, 2021). "This involved VCAM-1, a pro-inflammatory molecule that enhances monocyte–endothelial adhesion and is a key event in initiating atherosclerosis, and MMP-9 that plays an important role in endothelial dysfunction by triggering apoptosis and inflammation." (PMID 33388835, 2021). "VCAM-1 is a good target for the detection of existing atherosclerosis due to its highest abundance among atherosclerosis-related adhesion molecules." (PMID 33464410, 2021). "To investigate the mechanism of GsdmD in promoting atherosclerosis, we also probed the aortic protein extracts for VCAM-1 expression levels." (PMID 34395445, 2021). "On the endothelial surface, VCAM-1 is colocalised with proteins that promote its function in the first stage of atherosclerosis." (PMID 33138124, 2020). "A more recent study in 2018 employed PET/MRI imaging of atherosclerosis in rabbits while testing nanobodies against 3 different molecular targets: VCAM-1, LOX-1 and MMR47." (PMID 31903161, 2020). "Many clinical investigators have measured the levels of soluble ICAM-1 and VCAM-1 as the potential biomarkers for endothelial dysfunction and early atherosclerosis." (PMID 32089647, 2020). "A common feature of the inflammatory process in psoriasis and atherosclerosis is leukocyte migration, to which VCAM-1 and E-selectin significantly contribute." (PMID 32942670, 2020). "Canagliflozin was shown to reduce vascular inflammation and atherosclerosis by suppressing vascular cell adhesion molecule-1 (VCAM-1) and monocyte chemotaxis protein-1 (MCP-1) expression." (PMID 32879422, 2020). "In molecular imaging, vascular cell adhesion molecule-1 (VCAM-1) is a promising target for the non-invasive detection of atherosclerosis and for the assessment of novel antiatherogenic treatments." (PMID 33138124, 2020). "The authors suggested conjugating antibodies or binding peptides to target inflammatory markers, such as vascular cell adhesion molecule 1 (VCAM-1) for atherosclerosis and neutrophil cytosolic factor 1 for rheumatoid arthritis." (PMID 32660042, 2020).
atherosclerosis (continued). "Asiaticoside has been found to reduce endothelial permeability; it can effectively protect the occurrence of atherosclerosis by lowering the levels of intercellular adhesion molecule-1, vascular cell adhesion molecule-1, and E-selectin." (PMID 33013406, 2020). "Enhanced ICAM-1 and VCAM-1 expression, thus endothelial activation involved in atherosclerosis, was reported after acute and chronic distribution of IS by Six and colleagues." (PMID 33456671, 2020). "Previous study has demonstrated that targeting VCAM-1 with nanoparticles can be effectively utilized in the treatment of atherosclerosis." (PMID 32314783, 2020). "VCAM-1 is expressed in endothelial cells (ECs) and smooth muscle cells (SMCs), and induces atherosclerosis." (PMID 32325897, 2020). "Genetic depletion of NEXN-AS1 dramatically increased atherosclerosis in ApoE–/– mice, with concurrent increases in markers of vascular inflammation such as VCAM-1, ICAM-1, TNF-α, and MCP-1." (PMID 33021969, 2020). "The interaction between monocytes and endothelial cells through VCAM-1 expression induced by TNF-α is important for atherosclerosis development." (PMID 32218307, 2020). "For instance, the plant-derived antioxidant 3-hydroxyanthranilic acid (HA), was found to induce HO-1 expression and to inhibit both VCAM-1 expression and NF-kB activation by promoting Nrf2 translocation to suppress inflammation in atherosclerosis." (PMID 33238435, 2020). "In the setting of atherosclerosis, P-selectin, E-selectin, and VCAM1 are involved in monocyte rolling on inflamed aortic endothelium." (PMID 32101593, 2020). "The soluble forms of adhesion molecules, including ICAM-1, VCAM-1, and E-selectin, induce inflammatory activity in the dysfunctional endothelium in patients with atherosclerosis and diabetes." (PMID 32397494, 2020). "Prior studies that have noted the importance of VCAM1 mainly focused on vascular inflammatory diseases and immune diseases, such as atherosclerosis, myocardial infarction, idiopathic pulmonary fibrosis, and rheumatoid arthritis." (PMID 32793471, 2020). "Accumulating evidence indicates that VCAM‐1 is involved in the process of atherosclerosis, as well as NIH." (PMID 32741140, 2020). "Several studies have highlighted the use of CEU molecular imaging of VCAM-1 to evaluate the degree of inflammation in atherosclerosis." (PMID 33138124, 2020). "VCAM-1 is a pro-atherosclerotic adhesion molecule that plays an important role in the occurrence and development of atherosclerosis and plaque instability, and can promote leukocyte recruitment of atherosclerotic plaques." (PMID 33644113, 2020). "In this review, we focus on the imaging of vascular cell adhesion molecule-1, an adhesion molecule involved in the first stages of the development of atherosclerosis." (PMID 33138124, 2020). "ICAM-1 and VCAM-1 have been proposed as early biomarkers of changes in the artery wall and to play a major role in the development of atherosclerosis; therefore, both are considered preclinical markers of endothelial dysfunction." (PMID 32433661, 2020). "Studies have shown that ICAM-1 and VCAM-1 levels are elevated in patients with atherosclerosis, and the baseline ICAM-1 level is reportedly significantly associated with incident myocardial infarction and carotid atherosclerosis." (PMID 32433661, 2020). "The whole development process of atherosclerosis is quite significant: leukocyte recruitment induced by vascular cell adhesion molecule-1 (VCAM-1) under a high-fat environment, foam cell formation, and collagen degradation in blood vessels." (PMID 33339407, 2020). "The activation of vascular cell adhesion molecule 1 (VCAM-1) in vascular endothelial cells has been well considered implicating in the initiation and processing of atherosclerosis." (PMID 33274004, 2020). "Some findings indicated that atherosclerosis promoted low shear stress by activating the soluble form of VCAM-1." (PMID 32686027, 2020).
atherosclerosis (continued). "Our previous work has labeled anti-VCAM-1 scFv with fluorescent dye and radionuclide to synthesize imaging probes for atherosclerosis detection, and these probes demonstrate excellent imaging properties in both mouse and rabbit atherosclerotic lesions." (PMID 30804723, 2019). "We had previously used a peptide with affinity for VCAM-1 to successfully target liposomes to activated endothelium in atherosclerosis and cancer." (PMID 31382634, 2019). "The augmented response of MCP‐1, ICAM‐1 and VCAM‐1 to a given concentration of urate would stimulate downstream inflammation and thereby induce atherosclerosis progressing to a greater extent than controls in vitro." (PMID 30690853, 2019). "Using this VINP (VCAM-1 internalizing nanoparticle), they demonstrated the feasibility of non-invasively imaging of VCAM-1 expression in atherosclerosis ApoE−/− mice." (PMID 31440854, 2019). "Requirement of VCAM-1 for the initiation of atherosclerosis was shown using a Vcam1D4D/LDL receptor-knockout mouse model." (PMID 30858489, 2019). "Disturbed flow and low magnitude shear stress act through ER stress to promote vascular cell adhesion molecule 1 expression and monocyte adhesion to the endothelium, early events in atherosclerosis." (PMID 31359205, 2019). "In this study both ICAM-1 and VCAM-1 were correlated with risk for future CVD and ICAM-1 also with subclinical atherosclerosis, in line with previous studies." (PMID 31381601, 2019). "Both association with ERK5 and phosphorylation of S496 inhibit ERK5 transcriptional activity, which causes inhibition of KLF2 promoter activity, decrease of eNOS expression and increase of VCAM-1 expression, leading to atherosclerosis." (PMID 30813401, 2019). "In the early stage of atherosclerosis, oxidative stress in endothelial cells can induce the expression of cellular adhesion molecules such as vascular cell adhesion molecule 1 (VCAM-1), which helps monocytes in the blood bind to endothelial cells." (PMID 31248152, 2019). "Recent studies also suggested that soluble adhesion molecules, including ICAM-1, E-selectin, VCAM-1, and P-selectin, play an important role in the pathogenesis of atherosclerosis." (PMID 31771561, 2019). "Previous studies have shown that treatment with anti-VCAM-1 antibody inhibits leukocyte adhesion, attenuates atherosclerosis, decreases plaque inflammation, and improves plaque stability in ApoE (−/−) mice." (PMID 31300040, 2019). "This study was aimed to explore ICAM-1 and VCAM-1 expression of cardiac tissue from the early progression of atherosclerosis in dyslipidemia in Sprague Dawley rat model." (PMID 30505360, 2018). "Like ECs, VSMCs also express intercellular adhesion molecule 1 (ICAM-1) and vascular cell adhesion molecule 1 (VCAM-1) in atherosclerosis, restenosis, and transplant vasculopathy." (PMID 30406116, 2018). "Atherosclerosis is most likely initiated by the damage of endothelial cells due to flow disturbances, which lead to over-expression of vascular cell adhesion molecule-1 (VCAM-1), which provokes recruitment of monocytes and T lymphocytes." (PMID 29435774, 2018). "VCAM-1 plays a dominant role in the migration of monocytes to the vessel wall and in the initiation of inflammation and atherosclerosis." (PMID 29474366, 2018). "Ox-LDL induces endothelial dysfunction and changes of intercellular adhesion molecule-1 (ICAM-1), vascular cell adhesion molecule-1 (VCAM-1), and E-selectin, which are involved in the pathogenesis of atherosclerosis." (PMID 30050659, 2018). "In atherosclerosis, VCAM1 is the first adhesion molecule expressed before atherosclerotic plaque development." (PMID 30388809, 2018). "It is assumed that VCAM-1 plays a role in the pathogenesis of cardiovascular disease, especially atherosclerosis and rheumatoid arthritis." (PMID 30647815, 2018).
atherosclerosis (continued). "Loss of eNOS function and the resultant loss of NO in the eNOS–/– mouse leads to endothelial cell dysfunction, increased macrophage recruitment via increased vascular VCAM-1 expression and ultimately accelerated atherosclerosis." (PMID 29596571, 2018). "As previously reported, proinflammatory cytokine levels were increased concurrently with elevated circulating VCAM-1 in atherosclerosis." (PMID 30524759, 2018). "Based on our data, we conclude that the effects of butyrate and propionate on VCAM-1 expression were probably mediated by inhibition of HDACs thereby inhibiting the subsequent immune cell adhesion and preventing the development of atherosclerosis." (PMID 29875665, 2018). "The upregulation of vascular cell adhesion molecule-1(VCAM-1) on vascular endothelium plays a great role in the progression of atherosclerosis (AS)." (PMID 28982198, 2017). "VCAM-1 is fundamental to the recruitment of blood monocytes to sites of endothelial activation and contributes to leukocyte recruitment in atherosclerosis and AMI." (PMID 28878126, 2017). "Early en-face immunohistochemical staining in animal studies of atherosclerosis demonstrates the upregulation of VCAM-1 (vascular cell adhesion molecule-1) in turbulent flow sites in hyperlipidaemic animals compared to wild-type animals." (PMID 28465628, 2017). "In human plasma-derived EVs, there were significant increases in P selectin (CD62p) (13.7-fold, P < 0.05; n = 8) and VCAM-1, (2.3-fold, P < 0.001) compared with control stable atherosclerosis patients." (PMID 28878126, 2017). "VCAM-1 provides robust adhesion and mediates the recruitment of rolling-type cells into atherosclerosis lesions depending on α4β1 integrin." (PMID 28241014, 2017). "The interaction of endothelial cells and monocytes in atherosclerosis is mediated through adhesion molecules, among which are VCAM-1 and ICAM-1." (PMID 28593025, 2017). "In this study, ultrasound molecular imaging was performed to monitor the inflammation injuries in the onset and progression of atherosclerosis with microbubbles targeted to VCAM-1." (PMID 28982198, 2017). "VCAM-1 was reported to be critical for early atherosclerosis as genetic deletion of VCAM-1 greatly attenuates atherosclerosis in mice." (PMID 28963466, 2017). "In conclusion, our study demonstrated that CEU molecular imaging can be used to noninvasively detect the VCAM-1 expression on the endothelium in the procession of atherosclerosis." (PMID 28982198, 2017). "These pathophysiologically ‘inducible’ endothelial adhesion molecules, such as VCAM-1 (vascular cell adhesion molecule-1) and P-selectin, have the potential to serve as attractive biomarkers for imaging inflammation in atherosclerosis." (PMID 28044245, 2017). "CEU molecular imaging can be used to noninvasively detect the VCAM-1 expression on the endothelium in the progression of atherosclerosis." (PMID 28982198, 2017). "Previously in the same populations, we measured several circulating biomarkers related to atherosclerosis, and reported that chronic exposure to arsenic was positively associated with ICAM-1, VCAM-1 levels, and negatively associated with HDL-C." (PMID 28399171, 2017). "Adhesion molecules (ICAM-1 and VCAM-1) expressed by endothelial cells are involved in the recruitment and transendothelial migration of leucocytes leading to the initiation of atherosclerosis." (PMID 28399171, 2017). "The role of VCAM-1 in the inflammatory initiation of atherosclerosis is well established in animal models." (PMID 28044245, 2017). "Several cytokines (e.g. IL1β, IL6, and TNFα) are known to stimulate the expression of ICAM-1 and VCAM-1, two important molecules involved in the development of atherosclerosis." (PMID 27277003, 2016). "It was manifested as an increased expression of inflammatory molecules (IL-6 and VCAM-1) and decreased anti-atherosclerosis factor eNOS." (PMID 26890696, 2016).
atherosclerosis (continued). "Using this same mouse model, targeted microbubbles to VCAM-1 for CEUS imaging was used to investigate also the effect of statins to this early atherosclerosis process." (PMID 26206524, 2016). "Atherosclerosis PCR array and qPCR analyses showed upregulation of adhesion molecules such as intercellular adhesion molecule-1, vascular cell adhesion molecule-1, and E-selectin in HAECs upon SAA stimulation." (PMID 27799725, 2016). "Expression of CAMs such as ICAM-1, VCAM-1, and E-selectin mediates proinflammatory state and leads to formation of atheroma resulting in atherosclerosis." (PMID 27366195, 2016). "A number of specific targeted ultrasound probes has been tested in vivo for assessing biomarkers such as VCAM-1, P-selectin and von Willebrand factor in genetically modified mouse models of atherosclerosis." (PMID 27618031, 2016). "Endothelial activation is the initial event of atherosclerosis development and is activated by expression of multiple cell adhesion molecules including VCAM-1, ICAM-1 and E-selectin." (PMID 27799085, 2016). "In a mouse model of age-dependent atherosclerosis, ultrasound molecular imaging of the proximal thoracic aorta was performed with microbubbles targeted to P-selectin and VCAM-1 in order to detect a lesion-prone vascular phenotype." (PMID 26206524, 2016). "In this study, elevated expression level of VCAM-1 by periodontitis were detected in the Lig group, suggesting that periodontitis promotes the development of atherosclerosis by exacerbating aortic inflammation." (PMID 27386384, 2016). "The NF-κB transcriptional factor drives the expression of chemokines and adhesion molecules, such as ICAM-1 and VCAM-1, which recruit monocytes to diseased endothelium and initiates the development of atherosclerosis." (PMID 27249230, 2016). "Correlation analysis showed that the SYNTAX score (i.e., the lesion severity) was positively correlated with the VCAM-1 expression in atherosclerosis (r=0.532, P<0.01)." (PMID 26622332, 2015). "Several studies have demonstrated that, in addition to endothelial cells, VSMCs also express ICAM-1 and VCAM-1 in atherosclerosis and vascular diseases." (PMID 25716870, 2015). "VCAM-1 is expressed by vascular endothelial cells and plays an important role in monocyte or lymphocyte rolling and adhesion in early-onset atherosclerosis and in the inflammatory process." (PMID 26221595, 2015). "In this experimental model, expression of ET-1 and inducible adhesion molecules such as ICAM-1 and VCAM-1 in the arterial wall represented a key event in the development of atherosclerosis." (PMID 26504474, 2015). "In our apoE-/- mouse model of atherosclerosis, arsenic increased vascular expression of VCAM-1 and monocyte expression of active CD29." (PMID 26332580, 2015). "Accordingly, it has been shown that microbubble contrast agents targeted to VCAM-1 or P-Selectin can detect vascular inflammation not only in advanced atherosclerosis but also at lesion-prone sites in murine models of early atherosclerosis." (PMID 25938969, 2015). "Atherosclerosis is initiated with lipid oxidation by inducing the expression of vascular cell adhesion molecular-1 (VCAM-1)." (PMID 26080030, 2015). "In support of this view, suppression of VCAM-1 has been shown to protect against atherosclerosis in an animal model." (PMID 26066045, 2015). "In murine models of atherosclerosis, slow rolling of monocytes on the surface of atherosclerotic plaques appears to be largely mediated by VCAM-1." (PMID 25938969, 2015). "Some authors have suggested that ICAM-1 is predictive in initially healthy people and VCAM-1 in patients with atherosclerosis." (PMID 25784313, 2015). "The presence of atherosclerotic lesions was confirmed with Sudan IV and autoradiography; the authors concluded that radiolabeled-B2702-p has potential for imaging VCAM-1 in atherosclerosis." (PMID 25741532, 2015).